DLL3 (delta like canonical Notch ligand 3)
Diseases named in the same sentence as DLL3 in open-access papers (continued):
Sharing a sentence is not in itself a finding about the gene and the disease.
tumor (continued). "Furthermore, the majority of these were highly co-expressed at protein level with the notch ligand DLL3, which was previously identified as a proneural tumor marker." (PMID 26295306, 2015). "Beyond impaired differentiation, DLL3 overexpression promotes tumor growth, epithelial-to-mesenchymal transition, and metastasis through the regulation of Snail, Slug, and Twist, and may interact with pathways such as Wnt/β-catenin and PI3K/Akt to enhance tumor survival." (PMID 41562777, 2026). "However, the biomarker’s pathophysiological duality complicates interpretation: while promoting metastasis via Snail-mediated EMT, DLL3 simultaneously correlates with immunosuppressive tumor microenvironment (TME) features including decreased CD8+ T-cell infiltration and increased PD-L1 expression." (PMID 40496850, 2025). "However, DLL3 expression is low in some SCLC patients with high non‐NE tumor cells." (PMID 40285610, 2025). "Notably, our study revealed that patients with an expression pattern of PDL1 >1% and high DLL3 expression (=100%) represent a distinct subpopulation of SCLC patients who may have a more treatment-sensitive tumor." (PMID 38468968, 2024). "However, in a subsequent phase II TRINITY study for SCLC patients with multiple prior treatments (NCT02674568), the ORR was lower at 12.4% in all participants, 14.3% with ≥25% of tumor cells positive for DLL3, and 13.2% with ≥75% of tumor cells positive for DLL3, respectively." (PMID 39070179, 2024). "Therefore, only the expression of DLL3 in the tumor cells at the mRNA or protein level could be considered as a prognostic biomarker for PDAC." (PMID 37893184, 2023). "Therefore, DLL3 may suppress tumor development and metastasis by regulating immune responses and inhibiting various signaling pathways." (PMID 36338696, 2022). "However, in this study, only a few cases showed low DLL3 expression, and after adjusting for age, tumor size, and stage, DLL3 expression was no longer associated with OS." (PMID 34692726, 2021). "When incorporated as building blocks into a trispecific T cell engager (Tri-TCE) targeting DLL3, CD3, and CD28, the anti- CD28 VHHs conferred superior tumor specific cytotoxicity compared to a bispecific T cell engagers (Bi-TCEs) targeting only DLL3 and CD3." (PMID 42079579, 2026). "Among the recent advances in the treatment of extensive-stage SCLC is the bispecific T-cell engager, tarlatamab, which targets DLL3 and CD3 to facilitate T-cell lysis of tumor cells." (PMID 41256964, 2025). "DLL3 functions as a notch pathway inhibitor that is upregulated and expressed on the surface of SCLC tumor cells." (PMID 40507328, 2025). "DLL3 acts by inhibiting the Notch signaling pathway and is up-regulated on the cell surface of SCLC tumor cells, making it an ideal therapeutic target." (PMID 41256964, 2025). "ADCs represent a promising class of therapeutics for SCLC, driven by the selective overexpression of target antigens such as DLL3, B7-H3, TROP-2 and SEZ6 in tumour tissue, which provides a clear rationale for their use." (PMID 41463450, 2025). "DLL3 expression is regulated by the transcription factor ASCL1, which drives neuroendocrine cell differentiation and correlates with tumor-initiating potential." (PMID 41200177, 2025). "By recognizing and ligating CD3 (expressed on the cell membrane of T cells) and DLL3 (expressed on the cell membrane of NET), it promotes T cells to recognize NET cells and activates T cell-mediated tumor lysis." (PMID 40746825, 2025). "Tarlatamab (AMG 757), a bispecific T‐cell engager combining DLL3 and CD3, can induce T‐cell‐mediated tumour lysis, increase the number of effector T‐cells near the tumour and enhance anti‐tumour effects." (PMID 40847555, 2025). "Daily oral administration of HOC in a nude mouse NEPC xenograft model markedly suppressed the tumor expression of EPHA3 and BRN2, along with their downstream effectors EZH2, ASCL1, and DLL3 and neuroendocrine markers SYP and CHGA." (PMID 41514539, 2025).
tumor (continued). "As the first-in-class DLL3 BiTE, tarlatamab recruits T cells to DLL3-expressing tumors, triggering MHC-I-independent activation, granzyme/perforin release, and tumor lysis." (PMID 40496850, 2025). "Finally, we conducted a gene network analysis of the DEFA gene and found that there were tumor-suppressor-related genes associated with DEFA, including FGF21 and ITLN1, as well as tumor-promoting genes associated with DEFA, including GNB3, CRB2, DIO3, HPD, and Dll3." (PMID 41009818, 2025). "In conclusion, our study provides a comprehensive overview of the expression landscape of DLL3 in NET and NEC, highlighting significant differences between various histopathological subtypes and the primary tumour’s localisation." (PMID 40153138, 2025). "One promising alternative strategy is the use of BiTEs, which bind DLL3 on tumor cells to CD3 on CTLs, thereby inducing T-cell activation, inflammatory cytokine release, and CTL-mediated tumor cell death." (PMID 41194225, 2025). "T-cell engagers (TCEs) offer a new frontier by directly linking T-cells to cancer cells via specific tumor antigens (like PSMA, STEAP1, and DLL3), bypassing traditional immune recognition." (PMID 40507301, 2025). "Emerging therapies targeting DLL3, such as bispecific T-cell engager (BiTE) and chimeric antigen receptor (CAR) T cells, show promising anti-tumor activity in clinical trials and synergize with immune checkpoint inhibitors." (PMID 40496850, 2025). "This high prevalence of DLL3 expression in SCNEC aligns with previous studies in pulmonary SCNEC, that highlighted the therapeutic potential of DLL3 for these tumours." (PMID 40153138, 2025). "Rovalpituzumab tesirine (SC16LD6.5), an antibody‐drug conjugate targeting DLL3, has shown promising results in phase I studies against SCLC and large‐cell NE tumours, demonstrating encouraging single‐agent anti‐tumour activity and a manageable safety profile." (PMID 40847555, 2025). "A detailed transcriptome analysis of UCEC showed significant downregulation of miR-508-5p in tumor tissues, with bioinformatics predictions identifying a potential binding site for miR-508-5p on the 3’UTR of DLL3." (PMID 40066092, 2025). "In recent research, combining DLL3-targeted therapies with ICIs has demonstrated notable efficacy in addressing SCLC’s characteristic immune evasion, often seen as a “cold” tumor environment." (PMID 39703856, 2024). "Among T-cell engager molecules, the most clinically advanced molecule is tarlatamab, a compound that bispecifically binds both DLL3 and CD3 leading to T-cell-mediated tumor lysis." (PMID 38958823, 2024). "Their preclinical investigations, utilizing an anti-DLL3 monoclonal antibody conjugated to IR700, demonstrated significant tumor growth suppression and survival benefits in murine models of SCLC." (PMID 39703856, 2024). "Ligand-receptor analysis uncovered several significant interaction channels, including ligands that were distinctively upregulated in the tumor cells such as CD24, VEGFA, DLL3, and DLK1." (PMID 38358826, 2024). "Tumor-wide (100%) positivity was exhibited only for four event-case pairs (PTPRZ1-03 in tumor T2; NCAM1-01 in T24; DLL3-02 in tumors T15 and T16)." (PMID 38493204, 2024). "It has been described a dual role for the Notch receptor (Notch 1–4)-ligand (JAG1, JAG2, DLL1, DLL3 and DLL4) pathways as oncogenic or tumor suppressors." (PMID 36745330, 2023). "Tarlatamab (TMG 757) is a “first-in-class DLL3-targeted bispecific T-Cell engager” that binds to DLL3 and CD3 receptors, activating T-cell mediated tumor cell lysis." (PMID 37509621, 2023). "DLL3-targeted Bispecific T-cell Engager (BiTE) molecules and chimeric antigen receptors (CAR) T cells are in development to promote the tumor-suppressive functions of DLL3 and to avoid oncogenicity." (PMID 36381237, 2022).
tumor (continued). "DLL3 is not only involved in SCLC, but is also expressed in other tumor types of neuroendocrine origin, including melanoma, glioblastoma multiforme, small cell bladder cancer and castration-resistant prostate cancer." (PMID 36530878, 2022). "Despite the cessation of the TAHOE trial, DLL3 remains a high-value target in SCLC due to its high, homogeneous expression on the surface of tumor cells and its low, relatively restricted, cytoplasmic expression in normal cells." (PMID 31215500, 2019). "Recently, first-in-human, first-in-class, open-label phase 1 study of a DLL3-targeted antibody-drug conjugate was published, paving the way for the treatment of patients with SCLC, expressing DLL3 on the tumor cells." (PMID 31109352, 2019). "For example, DLL3 has emerged as a critical therapeutic target for SCLC, with related antibody‐drug conjugates and bispecific T‐cell engagers demonstrating promising anti‐tumour activity in clinical trials." (PMID 40847555, 2025). "DLL3 expression is not uniform across tumor cells that constitute a tumor and among tumor cells of different tumors." (PMID 40284515, 2025). "Expression of DLL3 (any degree) was observed in 300/1294 (23.2%) NEN, while 994 (76.8%) neoplasms were DLL3 negative." (PMID 40153138, 2025). "DLL3, widely expressed in SCLC tumor cells, represents a promising therapeutic target." (PMID 40563292, 2025). "Similarly, trispecific antibodies targeting DLL3, CD3, and CD137 amplify T-cell co-stimulation, demonstrating superior tumor control compared to conventional BiTEs in vivo." (PMID 40496850, 2025). "Among these eight tumors, six expressed DLL3 focally and weakly and seven expressed SEZ6; interestingly, the aggressive immature PIT1-lineage tumor was negative for DLL3 but expressed SEX6 diffusely (H-score 200)." (PMID 40699376, 2025). "Among the ligands, DLL1 regulates cell-cell communication, DLL3 inhibits apoptosis induction, DLL4 activates the NF-κB pathway, promoting VEGF expression; JAG-1 promotes angiogenesis, and JAG-2, upon binding Notch-2, activates tumor cell proliferation." (PMID 41200177, 2025). "Tarlatamab (AMG757), a DLL3-targeting BiTE engineered by Giffin’s team, demonstrates enhanced pharmacokinetics and low picomolar potency against SCLC cells in vitro, coupled with robust tumor growth inhibition in preclinical models." (PMID 40496850, 2025). "Between May 28, 2024, and February 10, 2025, six patients with DLL3 IHC-positive GEP NENs underwent [89Zr]Zr-DFO-SC16.56 immunoPET-CT imaging, which delineated DLL3-avid tumor lesions in five of six patients (two of two GEP NECs, three of four G3 PanNETs)." (PMID 41264896, 2025). "Among the six pairs with changes in DLL3 expression between the primary tumour and metastasis, an increase in DLL3 expression was observed in five cases, mostly from a DLL3 negative primary to a DLL3 positive metastasis." (PMID 40153138, 2025). "Delta-like ligand 3 (DLL3), a noncanonical ligand of the Notch pathway, has emerged as a key driver of tumor progression and poor clinical prognosis in NEPC." (PMID 41514539, 2025). "Finally, ligands, such as DLL3, play a crucial role in the differentiation plasticity of SCLC tumor cells, influencing cell proliferation, EMT, chemotherapy resistance and the expression of immune biomarkers." (PMID 40563292, 2025). "Preclinical models have shown strong anti-tumour responses in various solid malignancies: TF- or PD-L1-targeted CAR-NK cells in TNBC, c-Met CAR-NK cells with DAP10 co-stimulation in LUAD, and DLL3-specific CAR-NK cells in SCLC, which exhibited effective tumour suppression and immune infiltration." (PMID 40624498, 2025). "Furthermore, our data demonstrate high expression of Notch ligands (DLL3, DLK1) in tumor cells, indicating a possible role for these ligands in the recruitment and regulation of TAN and TAM within the bone metastatic microenvironment." (PMID 38358826, 2024).
tumor (continued). "In a real-world study of DLL3 as an SCLC therapeutic target, positive DLL3 expression (defined as ≥25% of tumor cells) was identified in 895/1050 (85%) patients with one specimen and evaluable DLL3 expression; 719/1050 (68%) patients had high DLL3 expression (defined as ≥75% of tumor cells)." (PMID 39392394, 2024). "The non-tumor thyroid was negative for DLL3 expression, except for granular staining related to colloid content observed in some normal follicles." (PMID 38958823, 2024). "In summary, DLL3-targeted therapies combined with ICIs represent an innovative and promising approach to treating SCLC, offering both direct tumor targeting and immune modulation to achieve sustained anti-tumor responses." (PMID 39703856, 2024). "While DLL3 inhibition with SC16LD6.5 markedly inhibited tumor growth in NEPC cell lines and PDX models, DLL3 was not identified as a master regulator for NEtD, as its inhibition did not consistently decrease NE markers." (PMID 39372390, 2024). "Overall, these negative correlations reinforce the connection between DLL3 in the tumor microenvironment and NOTCH1." (PMID 37893184, 2023). "A study of 1073 SCLC tumors concluded that DLL3 expression was independent of sex, age, tumor stage, performance status, and number of prior lines of therapy." (PMID 37355629, 2023). "For low DLL3-expressing tumors, a higher Notch signaling pathway activity is expected due to a negative correlation between DLL3 stroma expression and Notch tumor expression." (PMID 37893184, 2023). "One patient who received surgery alone and was DLL3 expression‐negative received postoperative radiation therapy to the margin of the tumor." (PMID 32691982, 2020). "Testing the antibodies on these cell cultures, using smears and cytoblocks, we showed that VenA is the only antibody that reliably stains tumor cells known to be DLL3 positive, and is also negative in cells that do not express DLL3." (PMID 31109352, 2019). "The antibody used in the clinical trial was the only which always positively stained the tumor cells obtained from cell cultures with known DLL3 expression and was negative on cells that did not express DLL3." (PMID 31109352, 2019). "In GEP-NET, however, DLL3 expression was comparably rare, which means that DLL3 may not be a therapeutic option for most of these neoplasms." (PMID 40153138, 2025). "While DLL3-targeted therapies show particular promise in tumors with high antigen homogeneity like SCLC, their clinical application in other cancers requires careful consideration of tumor microenvironment complexities, blood-brain barrier limitations, and compensatory signaling pathways." (PMID 40496850, 2025). "AMG119 is a DLL3-CAR T-cell product consisting of a DLL3 antigen-binding domain-targeting, CD28, 4-1BB co-stimulatory binding domain-conjugated CD3 domain autologous inactivating lentiviral vector, which has shown long term anti-tumor activity in preclinical studies in DLL3-expressing SCLC cells." (PMID 39897044, 2025). "By combining the CD47 blockade with a tumor-specific antigen (e.g., CD47 × DLL3, CD47 × HER2, or CD47 × CLDN 18.2), it may be possible to selectively restore macrophage-driven tumor clearance while minimizing systemic toxicity associated with global CD47 inhibition." (PMID 40508202, 2025). "Emerging data suggest that the interplay between DLL3 and PD-L1 may depend on tumor microenvironmental cues rather than intrinsic subtype biology." (PMID 40496850, 2025). "To characterize the heterogeneity of TROP2, DLL3, and CEACAM5 expression, we quantified the hypergeometric probability of concordant binarized H-scores (both ≥20 or both <20) for random pairs of samples from a given patient (intra-patient, inter-tumoral) or from the same tumor (intra-tumoral)." (PMID 38196594, 2023).
tumor (continued). "Despite the absence of available molecularly targeted therapies in SCLC, the application of ADCs may represent a potential treatment strategy that takes advantage of the intrinsic molecular characteristics exhibited by the tumor cells, such as the overexpression of TROP2, DLL3, B7-H3, and CECAM5." (PMID 38001628, 2023). "Therefore, the opposite effect of DLL3 on cancers suggests the necessity to check the activation patterns and potential roles of DLL3 in different tumor types without any initial impression." (PMID 35382168, 2022). "Tumor shrinkage occurred irrespective of DLL3 expression (range 55–300)." (PMID 36530878, 2022). "Other DLL3-targeting agents, such as T cell-redirecting therapies and immuno-oncology therapies (AMG 757 and AMG 119), may have a high effect and specificity for DLL3-positive SCLC tumor cells." (PMID 34568063, 2021). "None of the tumor cells in his primary tumor were positive for DLL3." (PMID 34385567, 2021). "But the expression of DLL3 was not correlated with sex (RR = 1.33, 95% CI = 0.98, 1.80; I2 = 0.0%, p = 0.064), smoking history (RR = 1.01, 95% CI = 0.58, 1.75; I2 = 72.1%, p = 0.967) and tumour stage (RR = 0.68, 95% CI = 0.44, 1.05; I2 = 66.6%, p = 0.081)." (PMID 32847588, 2020). "Lack of tumor recurrence was shown being due to depletion of DLL3+ CSCs." (PMID 30984612, 2019). "Moreover, SCLC cells develop resistance to agents that target DLL3 by reverting to a non-DLL3-expressing phenotype or using alternative signaling pathways, such as the Notch, Wnt/β-catenin, MAPK/ERK, and PI3K/AKT pathways, which ensure tumor cell survival and proliferation in the absence of DLL3." (PMID 40284515, 2025). "Therefore, when no biopsy from the primary tumour is available, DLL3 assessment in metastases may provide a reliable estimation of its expression in the primary site." (PMID 40153138, 2025). "Low-level DLL3 mRNA expression has been detected in pituitary, brain, and testis but, importantly, not on the cell surface of nonmalignant cells, making it an attractive tumor-specific target for antibody-drug conjugates, bispecific T cell engagers, and CAR T cells." (PMID 36951942, 2023). "Therefore, high DLL3 expression at the mRNA level could be considered a good prognostic biomarker for PDAC and could be easily quantified using real-time PCR with the resected tumor in clinical practice." (PMID 37893184, 2023). "SCLC cells express Notch inhibitors delta like non-canonical Notch ligand 1 (DLK1) and DLL3 (DLL3 is expressed as a neoantigen on the surface of some SCLC cells) or have inactivating mutations in the Notch pathways, leading to inactivation of the tumor suppression." (PMID 34531756, 2021). "SMARCA4 expression was positively correlated with multiple NE genes including SYP, CHGA, INSM1, DLL3 and NCAM1 and negatively correlated with non-NE factors REST, NOTCH2, and YAP1 in both SCLC cell lines and patient tumor databases." (PMID 39080761, 2024). "Tarlatamab (AMG 757) is a bispecific T-cell engager molecule (BiTE) which binds both DLL3 and CD3, leading to T-cell-mediated tumor lysis irrespective of MHC class I expression which is frequently downregulated in patients with SCLC." (PMID 38927637, 2024). "The DMR is situated within the DYRK1B gene, approximately 200 kbp distal to the DLL3 TSS, and is significantly correlated with DLL3, but not DYRK1B, gene expression in both primary tumor samples and cell lines." (PMID 32707835, 2020). "DLL3, however, was not CSC-specific since its expression was seen throughout the tumor, with most cells expressing it to some degree." (PMID 30984612, 2019). "DLL3 was expressed in 99/980 (10.1%) NET/TC/AC, with 37 (3.8%) showing a weak, 28 (2.9%) showing a moderate and 34 (3.5%) displaying a strong expression, while 881 (89.9%) neoplasms were completely DLL3 negative." (PMID 40153138, 2025). "However, there was no discernible variation in DLL3 levels between KIRC and non-tumor tissues." (PMID 37179118, 2023).